TRPA1 (transient receptor potential cation channel subfamily A member 1)
Diseases named in the same sentence as TRPA1 in open-access papers (continued):
Sharing a sentence is not in itself a finding about the gene and the disease.
COVID-19 (11 papers, 2020 to 2025). A disease caused by infection with severe acute respiratory syndrome coronavirus 2. "The transient receptor potential anchor protein type 1 (TRPA1), an injury receptor activated by tissue damage and inflammation, is implicated in coronavirus disease 2019 (COVID-19) and serves as an important target of PG." (PMID 40005144, 2025). "Furthermore, TRPV1/A1, implicated in the cough reflex, was confirmed in COVID-19 through induced cough challenges, demonstrating rapid relief with TRPA1/V1 agonists (green tea, curcumin, ginger, red pepper)." (PMID 38827576, 2024). "Therefore, it can be hypothesized that TRPA1 plays an important role in forming COVID-19-associated myocardial fibrosis, which provides a potential drug target for treating COVID-19-associated myocardial fibrosis." (PMID 39444690, 2024). "TRPA1, an excitatory ion channel originally associated with the receptor of mustard oil in sensory neurons, plays a pivotal role in detecting cysteine-reactive irritants and in augmenting sensory or vagal nerve discharges to evoke several COVID-19 symptoms including cough." (PMID 33425204, 2021). "A total of 6 hub genes were obtained, including: LDHA, TRPA1, PKP2, FBN2, ERO1A, FSCN1, all of which are risk factors for LUAD/COVID-19." (PMID 36157452, 2022). "We suggest that electrophilic ligands activate and desensitize TRPA1 and that they also activate Nrf2, thus blocking the activation of TRPA1 by reactive oxygen species (ROS) produced by COVID-19." (PMID 33425204, 2021). "We identified 230 LUAD/COVID-19 DEGs and constructed a risk score containing 7 genes (BTK, CCL20, FURIN, LDHA, TRPA1, ZIC5, and SDK1) that could classify LUAD patients into two risk groups." (PMID 35733175, 2022). "Activators of TRPA1 can help control symptoms such as coughing in COVID-19 patients." (PMID 36157452, 2022). "Additionally, TRPA1 has been implicated in POI through the regulation of gastrointestinal motility, and its interaction with Nrf2 in COVID-19 influences oxidative stress and inflammation, indicating its broad significance in disease pathophysiology and potential therapeutic interventions." (PMID 39273183, 2024). "TRPA1 and TRPV1 may provide a breakthrough in the treatment of symptoms of COVID-19." (PMID 37402746, 2023).
Hypertension (11 papers, 2014 to 2025). The presence of chronic increased pressure in the systemic arterial system. "The current study investigated the involvement of endothelial cell TRPA1 channels in the pathogenesis of hemorrhagic stroke associated with severe hypertension." (PMID 36793787, 2023). "Here, we tested the hypothesis that increased ROS generation associated with severe hypertension increases endothelial cell TRPA1 activity to dilate cerebral arteries." (PMID 36793787, 2023). "We also investigated the role of TRPA1 during hypertension-associated hemorrhagic stroke." (PMID 36793787, 2023). "Our group has recently demonstrated the protective role of the neuropeptide calcitonin gene-related peptide (CGRP) in hypertension, so we hypothesized that TRPA1 KO mice may show susceptibility to angiotensin II-induced hypertension and related morbidities." (PMID 25505598, 2014). "Although we were unable to isolate a TRPA1- or CGRP-dependent mechanism within the CA response, there remains a possibility that TRPA1 may be expressed at functional levels in mesenteric arteries and may influence development of the vascular dysfunction associated with hypertension." (PMID 25505598, 2014). "There is a growing body of evidence in the literature highlighting the involvement of TRP channels, including TRPM7/8, TRPV1, and TRPA1, in the pathophysiology of hypertension." (PMID 38255767, 2024). "Together, these findings suggest that enhanced ROS production during hypertension increases cerebral artery endothelial cell TRPA1 activity leading to vasodilation and expansion of hemorrhagic lesions." (PMID 36793787, 2023). "Induction of severe hypertension increased the capacity for ROS generation and TRPA1-dependent dilation of cerebral arteries by increasing the expression of NOX enzymes." (PMID 36793787, 2023). "Discussion: We conclude that endothelial cell TRPA1 channel activity increases cerebral blood flow during hypertension resulting in increased extravasation of blood during intracerebral hemorrhage events; however, this effect does not impact overall survival." (PMID 36793787, 2023). "TRPA1 expression in dorsal root ganglion (DRG) neurones was upregulated during hypertension (163% of baseline expression)." (PMID 25505598, 2014). "Hypertension was established within the first few days of angiotensin II infusion, with onset and magnitude being similar in TRPA1 WT and KO mice." (PMID 25505598, 2014). "In conclusion, our study provides a novel cardiovascular characterization of TRPA1 KO mice in a model of hypertension." (PMID 25505598, 2014). "In this study, we primarily investigated if TRPA1 deletion would alter cardiovascular phenotype and vulnerability to hypertension induced by angiotensin II infusion." (PMID 25505598, 2014). "Most strikingly, our results reveal a novel role for TRPA1 in controlling physical activity in vivo, where TRPA1 KO mice showed a preference for increased locomotion and physical exercise, which was exacerbated during hypertension." (PMID 25505598, 2014). "Unexpectedly, naïve TRPA1 KO mice also displayed physical hyperactivity traits at baseline, which was exacerbated during hypertension." (PMID 25505598, 2014). "Using the angiotensin II model of hypertension, we found TRPA1 to have a limited ability to modulate hemodynamics, however, some important differences to the inflammatory profile were observed." (PMID 25505598, 2014). "Furthermore, the thermosensitive receptors, TRPA1/TRPM8/TRPV1, which are expressed in the cardiovascular system, have been implicated in the pathogenesis of hypertension." (PMID 38255767, 2024). "For example, the activation of C-fibers by injecting capsaicin, a transient receptor potential vanilloid 1 (TRPV1) agonist, or mustard oil, a TRP ankyrin 1 (TRPA1) agonist, into the skin with neurogenic inflammation over the median nerve blocks the development of hypertension in rats." (PMID 32039692, 2020).
Hypertension (continued). "However, some significant differences were seen in TRPA1 KO mice during hypertension; notably, a trend for increased hypertrophy and a blunted increase in IL-6." (PMID 25505598, 2014). "Our original hypothesis was that cardiovascular phenotype of TRPA1 KO mice would be altered, producing sensitivity to hypertension." (PMID 25505598, 2014). "BW in TRPA1 WT and KO mice after 14 days of hypertension was similar." (PMID 25505598, 2014). "Our data suggest that blocking TRPA1 channels may not be helpful for treating hypertension-associated hemorrhagic stroke in a clinical setting." (PMID 36793787, 2023). "Thus, our data suggest that blocking TRPA1 channels may not be helpful for treating hypertension-associated hemorrhagic stroke." (PMID 36793787, 2023). "Therefore, TRPA1 likely plays a protective role in age-related cardiac fibrosis through inhibiting collagen deposition while may contribute to cardiac fibrosis after myocardial infarction and in the setting of hypertension through activating fibroblasts." (PMID 36103570, 2022). "This was determined using an angiotensin II (Ang II) model of hypertension, in which the blood pressure elevation induced by 14 days of subcutaneous Ang II infusion was indistinguishable between wild-type and Trpa1-KO mice." (PMID 34064835, 2021). "Our findings demonstrate that this is not the case, as both TRPA1 WT and KO mice developed similar levels of hypertension in this model." (PMID 25505598, 2014). "Alongside our results showing increased TRPA1 mRNA expression in DRG from hypertensive mice, these findings indicate a more prominent role for TRPA1 in the control of BP and inflammation could develop in scenarios with prolonged hypertension." (PMID 25505598, 2014).
injury (11 papers, 2010 to 2023). Damage inflicted on the body as the direct or indirect result of an external force, with or without disruption of structural continuity. "Certain TRPA1 genetic markers have been associated with specific characteristics, including central pain hypersensitivity, primary and secondary hyperalgesia, mechanical nociception, and cold hyperalgesia, following inflammation and nerve injury." (PMID 37893054, 2023). "Many neuropathic pain models induced by nerve injury are characterised by mechanical and cold hypersensitivity, suggesting a relevant role for TRPA1 as it is a key transducing channel in mechanical/cold-sensing nociceptors." (PMID 31197115, 2019). "Previous studies have demonstrated important roles for TRPV1, TRPM8, and TRPA1 in inflammation and nerve injury induced pain." (PMID 20205720, 2010). "Larger macrophage activation was found in Trpa1 KO mice in angiotensin II-induced kidney injury." (PMID 33806000, 2021). "In acute nerve injury and inflammation, macrophages infiltrating the site of injury undergo an oxidative burst, and generate ROS that promote tissue repair and induce pain via TRPA1." (PMID 33424587, 2020). "Therefore, TRPA1 and Gαq subunit (specifically, enhanced Gαq activation) should be considered as potential targets for regulating inflammation-induced sensitization during musculoskeletal trauma." (PMID 37250415, 2023). "TRPA1 and TRPV1 have been reported to be protective against the LPS-induced acute lung injury model." (PMID 32759721, 2020). "TRPA1 and TRPV1 channels are known to mediate inflammatory and nerve injury pain, making them key targets for pain therapeutics." (PMID 23497345, 2013). "TRPA1 might have a role in neurogenic inflammation and moderate nerve injury-related pain, whereas CGRP does not seem to be involved in these conditions." (PMID 37893054, 2023). "Moreover, TRPA1 channel was over-expressed in rat DRG neurons following peripheral inflammation and nerve injury, and cold hyperalgesia produced by inflammation and nerve injury was accompanied by the activation of the TRPA1 but not the TRPM8 channel." (PMID 27483289, 2016).
cardiac hypertrophy (10 papers, 2014 to 2024). "This assumption is supported by evidence of reduced fibrosis in TRPA1-deficient mice in models of scleroderma dermal fibrosis, cardiac hypertrophy, fibrosis, and corneal stroma healing." (PMID 38635081, 2024). "Although these changes have been shown to occur in cardiomyocytes involved in myocardial hypertrophy, the present research constitutes the first demonstration of TRPA1-associated DYRK1A changes in CFs and the involvement of these CFs in MI-related CMF transdifferentiation." (PMID 31217840, 2019). "A study on cardiac hypertrophy and fibrosis discovered that TRPA1 inhibition protected against cardiac hypertrophy and suppressed cardiac dysfunction through Ca2+-dependent signaling pathways and inhibition of M2 macrophage transition." (PMID 38635081, 2024). "In models of cardiac hypertrophy and fibrosis, increased TRPA1 expression in failing human hearts and hypertrophic mouse hearts suggests its involvement in cardiac hypertrophy." (PMID 38635081, 2024). "Increased cardiac weight, suggestive of cardiac hypertrophy, was observed in Trpa1fl/fl and Trpa1-ecKO mice treated with Ang II/HS/L-NAME compared to their untreated counterparts." (PMID 36793787, 2023). "TRPA1 was reported previously to be involved in reparative fibrosis after myocardial infarction and pressure overload-induced cardiac hypertrophy likely through regulating fibroblast activation." (PMID 36103570, 2022). "In this case, inhibition of TRPA1 would attenuate cardiac hypertrophy but increase atherosclerotic progression and worsen renal kidney injury." (PMID 34768891, 2021). "Comparable hypertensive responses to angiotensin II infusion were noted in both genotypes, but hypertensive TRPA1 KO mice showed blunted production of IL-6 and increased cardiac hypertrophy compared to WT mice." (PMID 25505598, 2014). "TRPA1 KO mice presented with more substantial cardiac hypertrophy, but blunted ability to increase IL-6 production; results which are difficult to reconcile." (PMID 25505598, 2014). "Importantly, older Trpa1-/- mice had enhanced cardiac fibrosis than older WT mice (P<0.05) while the two strains had similar degree of cardiac hypertrophy." (PMID 36103570, 2022). "Mice, treated with a TRPA1 antagonist, showed attenuated cardiac hypertrophy, decreased expression of several hypertrophic markers (atrial natriuretic peptide, brain natriuretic peptide, and β-myosin heavy chain), and less interstitial fibrosis compared to untreated animals." (PMID 34768891, 2021). "Additionally, TRPA1-selective inhibitors protected against cardiac hypertrophy and fibrosis by modulating M2 macrophage differentiation." (PMID 31217840, 2019). "Therefore, we added further experiments to assess the effect of TRPA1 on cardiac hypertrophy by silencing TRPA1." (PMID 30299584, 2018). "However, heart weight-to-tibia length and LV mass-to-body mass ratios both showed TRPA1 KO mice to develop significantly more cardiac hypertrophy than TRPA1 WT mice." (PMID 25505598, 2014). "Our findings reveal that older Trpa1−/− mice exhibited significantly increased left ventricular internal diameter and volume, impaired systolic and diastolic functions, and enhanced cardiac fibrosis compared to older WT mice, despite similar levels of cardiac hypertrophy between the two strains." (PMID 39323758, 2024). "Therefore, we should discuss whether TRPV1 and TRPA1 also contribute to cardiac hypertrophy." (PMID 30299584, 2018). "In our experiment, we could not exclude the damage effect of TRPV1 and TRPA1 activation on cardiac hypertrophy when ruthenium red and carvacrol were applied in vivo or in vitro." (PMID 30299584, 2018). "However, the effect of TRPA1 on cardiac hypertrophy was not clear." (PMID 30299584, 2018).
Crohn disease (10 papers, 2014 to 2025). A gastrointestinal disorder characterized by chronic inflammation involving all layers of the intestinal wall, noncaseating granulomas affecting the intestinal wall and regional lymph nodes, and transmural fibrosis. "There is elevated expression of TRPA1 in fibrotic lesions from patients with Crohn’s disease, and activation of TRPA1 channels in myofibroblasts is associated with reduced intestinal fibrosis after treatment with prednisolone or pirfenidone." (PMID 38612378, 2024). "Pain caused by Crohn’s disease likely involves neurogenic inflammation which seems to involve the ion channel transient receptor potential ankyrin 1 (TRPA1)." (PMID 31892361, 2019). "As TRPA1 is regarded to be involved in pain caused by neurogenic inflammation, its aberrant expression may contribute to typical symptoms of Crohn’s disease." (PMID 31892361, 2019). "Epigenetic alterations, including DNA methylation and histone modifications, modulate the expression of the TRPA1 gene, as for patients with Crohn’s disease with altered regulation of pain perception possibly related to TRPA1 promoter hypermethylation." (PMID 39770499, 2024). "Reactive oxygen species, which are capable of activating TRPA1, were shown to be produced in several gastrointestinal diseases, including Crohn’s disease." (PMID 31892361, 2019). "The TRPA1 promoter methylation appears to be dysregulated in patients suffering from Crohn’s disease, and this effect is most obvious when taking gender and age into account." (PMID 31892361, 2019). "Since the promoter methylation of TRPA1 was shown to influence pain sensitivity, we asked if the expression of TRPA1 is dysregulated in patients suffering from Crohn’s disease." (PMID 31892361, 2019). "TRPA1 was upregulated in colonic mucosa samples from Crohn’s disease patients." (PMID 37326902, 2023). "In human colon samples from patients suffering from ulcerative colitis or Crohn’s disease, TRPA1 was found to be strongly upregulated, suggesting dysregulation of TRPA1-expression to possibly contribute to the development, maintenance, or typical symptoms of IBD." (PMID 31892361, 2019). "Also, TRPA1 is highly expressed in the intestinal lamina propria and in the stenotic intestinal regions of Crohn’s disease (CD) patients, which increased TRPA1/heat shock protein 47 double-positive cells accumulation in the stenotic intestinal regions of CD patients." (PMID 35058918, 2021).